TERT (telomerase reverse transcriptase)
Diseases named in the same sentence as TERT in open-access papers (continued):
Sharing a sentence is not in itself a finding about the gene and the disease.
mantle cell lymphoma (2 papers, 2016 to 2019). Mantle cell lymphoma is a rare form of malignant non-Hodgkin lymphoma affecting B lymphocytes in the lymph nodes in a region called the ``mantle zone''. "Concurrent to this study, TERT promoter mutations were reported to be present in 33% of circulating mantle cell lymphoma." (PMID 27792139, 2016). "While we detected no TERT promoter mutations in our set of mantle cell lymphoma, there are a few possible reasons for this apparent discordance." (PMID 27792139, 2016). "Then the analyses of mantle cell lymphoma (MCL) using multi-color FISH unraveled the TERT rearrangement in 4/8 MCL-derived cell lines and 1/23 patients." (PMID 31285550, 2019).
microcephaly (2 papers, 2014 to 2020). A congenital or acquired developmental disorder in which the circumference of the head is smaller than normal for the person's age and sex. "We identified the candidate genes PPARGC1A, CTBP1, TRIO, TERT, and CCT5 that are associated with the neuropsychomotor delay, microcephaly, and neurological alterations found in our patient." (PMID 32625234, 2020). "The TERT gene has been reported as a candidate gene for Cri du Chat syndrome (OMIM#123450); the most important clinical features are a high-pitched cat-like cry, distinct facial dysmorphism, microcephaly, severe psychomotor and mental retardation." (PMID 25530804, 2014).
mood disorder (2 papers, 2016 to 2025). A cognitive disorder a disturbance in which the person's mood is hypothesized to be the main underlying feature. "For instance, it has been shown that chronic stress can lead to a secondary adaptation that suppresses TERT expression and TA, which could be the case for non-mood disorders." (PMID 40887790, 2025). "However, when stress becomes chronic, a secondary adaptation suppresses TERT expression and TA which might explain the opposite observation in non-mood disorders." (PMID 40887790, 2025).
Nephropathy (2 papers, 2012 to 2022). A nonspecific term referring to disease or damage of the kidneys. "To establish the role of TERT in kidney physiological regeneration, we used the Adriamycin-induced nephropathy model to cause a podocyte-specific insult and investigated the role of endogenous TERT in this context." (PMID 35149726, 2022). "Using a mouse model of Adriamycin-induced nephropathy, we find that the recovery of filtration function requires up-regulation of the endogenous telomerase component TERT." (PMID 35149726, 2022). "We first found that endogenous TERT is upregulated upon glomerular repair in a model of ADR-induced nephropathy, a process that involves the resolution of glomerular scarring and fibrosis that precludes regeneration." (PMID 35149726, 2022). "Overall, these results suggest that endogenous TERT expression is required for kidney filtration recovery and ECM remodeling, independently of its catalytic activity in telomere elongation, to achieve glomerular repair following ADR-induced nephropathy." (PMID 35149726, 2022).
ocular melanoma (2 papers, 2021 to 2023). A melanoma that arises from the structures of the eye or ocular adnexa. "The mutation that we found most frequent in CM is a TERT promoter mutation, congruent with other studies concerning ocular melanoma and cancer originating from other sites." (PMID 34071371, 2021).
Oncocytic Thyroid Carcinoma (2 papers, 2023 to 2024). "A total of 29 tumors (26 FTCs, 2 follicular thyroid tumors of uncertain malignant potential, and 1 oncocytic thyroid carcinoma) with known TERT promoter mutational status and TERT gene expression were assessed for 5hmC immunoreactivity using two antibodies (clones RM236 and 4D9)." (PMID 37486076, 2023).
oropharyngeal squamous cell carcinomas (2 papers, 2025). "Namely, in nearly half of OSCCs, TERT promoter mutations were found, while in oropharyngeal squamous cell carcinomas, their prevalence was as low as 1%, and that in larynx/hypopharynx as low as 12%." (PMID 40278994, 2025).
pancreatic ductal adenocarcinoma (2 papers, 2013 to 2024). An infiltrating adenocarcinoma that arises from the epithelial cells of the pancreas. "We used a diploid cell line derived from normal pancreatic ducts and immortalized with the TERT gene, hTERT-HPNE, and a commonly used hypertriploid pancreatic ductal carcinoma derived cell line, PANC-1, for our studies." (PMID 24053169, 2013).
Pancytopenia (2 papers, 2008 to 2021). An abnormal reduction in numbers of all blood cell types (red blood cells, white blood cells, and platelets). "Intriguingly, the overexpression of the RT domain of zTERT (without the TR-binding domain) as well as full-length zTERT rescues the TERT-deficient animals from pancytopenia, with a concurrent restoration of differentiation." (PMID 18846223, 2008). "Taken together, these results suggest that TERT is involved in both definitive and primitive hematopoietic waves, which may therefore be responsible for the subsequent pancytopenia in TERT deficient zebrafish embryos." (PMID 18846223, 2008).
paraganglioma (2 papers, 2021). A benign or malignant neoplasm arising from paraganglia located along the sympathetic or parasympathetic nerves. "Telomere maintenance involving TERT and ATRX genes has been recently described in metastatic pheochromocytoma and paraganglioma, reinforcing the importance of immortalization mechanisms in the progression of these tumors." (PMID 34638246, 2021).
parathyroid carcinoma (2 papers, 2019 to 2021). "However, these mutations seem fairly rare in parathyroid carcinomas, although these tumors in general express TERT protein." (PMID 33269427, 2021). "As of this, alterative mechanisms leading to increased TERT expression in parathyroid carcinomas are suspected." (PMID 33269427, 2021).
penile squamous cell carcinoma (2 papers, 2021 to 2022). "The aim of this study was to investigate the presence of TERT-p mutations in penile squamous cell carcinomas (SCCs) and their associations with clinicopathologic features." (PMID 33635430, 2021). "TERT amplifications have not been described in penile squamous cell carcinomas, so far." (PMID 36564761, 2022).
peritoneal mesothelioma (2 papers, 2022 to 2025). A benign or malignant mesothelial neoplasm that arises from the peritoneum. "In our cohort of pleural and peritoneal mesothelioma patients, the TERT promoter was mutated in 7.6% and in 4.7% of the cases, respectively." (PMID 36138075, 2022). "Our study aimed to clarify the mRNA expression of TERT in peritoneal mesothelioma (PeM), and to explore the relationship between its expression and the clinicopathological parameters and prognosis of patients with PeM." (PMID 39858033, 2025).
Phyllodes tumors of the breast (2 papers, 2017 to 2021). "TERT promoter hotspot mutations and TERT gene amplification have been reported in phyllodes tumors of the breast, suggesting that these genetic alterations might be the drivers of the progression from benign to malignant lesions in a subset of patients." (PMID 33863915, 2021). "Phyllodes tumors of the breast, as a group, displayed a significantly higher frequency of mutations affecting MED12 (59% vs 5%, Fisher's exact test, P = 0.0002) and the promoter of TERT (45% vs 0, Fisher's exact test, P = 0.0006) than adenosarcomas." (PMID 28267263, 2017).
Pituitary Adenomas (2 papers, 2014 to 2022). "TEP1, TERC, and TERT genes single nucleotide polymorphisms were analyzed to evaluate the associations with pituitary adenoma activity, invasiveness, and relapse." (PMID 35892421, 2022). "Thus, this study aimed to determine the relationship between the molecular markers of telomerase complex (TERC rs12696304, rs35073794, TEP1 rs1713418, rs1760904, and TERT rs2736098, rs401681) and the relative leukocyte telomeres length with the development of pituitary adenoma." (PMID 35892421, 2022).
pleura mesothelioma (2 papers, 2022 to 2023).
Pleural effusion (2 papers, 2020 to 2021). The presence of an excessive amount of fluid in the pleural cavity. "We established a novel cell line (PF49) from the malignant pleural effusion of a 68-year-old male patient with ATC that rapidly transformed from a BRAF and TERT promoter mutant PTC." (PMID 32591993, 2020).
poorly differentiated thyroid cancer (2 papers, 2019 to 2022).
psoriasis (2 papers, 2013 to 2017). An autoimmune condition characterized by red, well-delineated plaques with silvery scales that are usually on the extensor surfaces and scalp. "We explored the potential of N/TERT keratinocytes for generating in vitro inflammatory skin models for psoriasis by the addition of pro-inflammatory cytokines to N/TERT-HEEs." (PMID 28928444, 2017). "The expression of psoriasis-related host defence genes PI3 and DEFB433–35 (encoding SKALP/elafin and hBD2, respectively) was increased in both primary and N/TERT keratinocytes, but N/TERT keratinocytes showed a significantly stronger upregulation and this was most pronounced in N/TERT2G cultures." (PMID 28928444, 2017). "We found that the addition of Th17 cytokines, IL-17 and IL-22, to the N/TERT-HEEs most closely resembled psoriasis skin: presence of parakeratosis, lack of a stratum granulosum (and thus low levels of FLG and LOR), and induced levels of hBD2 and SKALP." (PMID 28928444, 2017).
pulmonary hypertension (2 papers, 2013 to 2023). Increased pressure within the pulmonary circulation due to lung or heart disorder. "It has been demonstrated that elevated telomerase reverse transcriptase (TERT) expression or activity is implicated in pulmonary hypertension (PH)." (PMID 36938425, 2023). "To our knowledge, we have demonstrated that the expression of telomerase reverse transcriptase (TERT) is enhanced in the pulmonary vasculature of pulmonary hypertension (PH) patients and experimental models of PH for the first time." (PMID 24376652, 2013). "Strategies that inhibit vascular TERT and 15-LO-2 expression of the lung may antagonize the loop and ameliorate the morbidity and mortality in patients with pulmonary hypertension." (PMID 24376652, 2013). "TERT and 15-LO-2 form a positive feedback loop and together promote proliferation and migration of pulmonary artery smooth muscle cells, creating a self-amplifying circuit which propels pulmonary hypertension." (PMID 24376652, 2013).
salivary gland tumor (2 papers, 2023 to 2025). "This indicates the importance of doing more research on TERT promoter gene mutations in patients with salivary gland tumors." (PMID 37383158, 2023). "Of 15 salivary gland tumor specimens, consisting of 5 benign tumors and 10 malignant tumors after DNA sequencing, TERT promoter region mutation was only seen in one of the adenoid cystic carcinoma samples, located at -146 bp upstream from ATG (chr5: 1,295,250 C>T)." (PMID 37383158, 2023). "Therefore, the present study aimed to investigate the mutation in the promoter region of TERT in benign and malignant salivary gland tumors." (PMID 37383158, 2023). "When specifically analyzing salivary gland tumors, TERT promoter mutations were not different when comparing malignant and benign tumors, though this promoter and its involvement are rarely investigated." (PMID 39831137, 2025).
sarcomatoid carcinoma (2 papers, 2021 to 2023). A malignant epithelial neoplasm characterized by the presence of spindle cells and anaplastic morphologic features. "The remaining TERT-p mutation detected in our study was c.-124C > A, which was found in both an excision and penectomy specimen of the same patient and was the only case of sarcomatoid carcinoma in our cohort." (PMID 33635430, 2021).
sarcopenia (2 papers, 2022). Progressive decline in muscle mass due to aging which results in decreased functional capacity of muscles. "As SMG7 is linked with telomerase reverse transcriptase (TERT), sarcopenia may be related to muscle cell senescence via microRNA-19533." (PMID 35241739, 2022).
seborrheic keratosis (2 papers, 2017 to 2024). A common benign skin neoplasm usually affecting older individuals. "All seborrheic keratosis lesions with TERT promoter mutations originated from the head/neck (OR 61.3, 95% CI 2.76-1359.24, p = 0.009)." (PMID 28410231, 2017). "However, in contrast, the TERT promoter mutations in seborrheic keratosis did not result in enhanced expression and may represent sheer passenger events due to lack of requisite transcription factors in the lesions." (PMID 28410231, 2017).
skin aging (2 papers, 2024 to 2025). The gradual irreversible changes in structure of skin that occur as a result of the passage of time.. "It has been suggested that TERT and telomerase can be modulated by external damages related to skin aging as well as by diet or nutraceutical compounds, especially those in herbs such as polyphenol compounds, flavonoids, and organic acids with antioxidant properties." (PMID 40573097, 2025). "The reduction in telomere length, a marker of aging, can be quantified by the diminished expression of TERT, and a decline in COL1A1 expression is correlated with skin aging." (PMID 39296334, 2024).
small cell carcinoma of the bladder (2 papers, 2014 to 2021). "In this study, we investigated TERT promoter mutations in small cell carcinoma of the bladder, prostate, lung and other primary sites." (PMID 25042800, 2014). "Most importantly, TERT promoter mutation can be used as a potential biomarker for bladder small cell carcinoma." (PMID 25042800, 2014). "High rates of TERT gene variants (80%) are common in bladder SCC but have also been detected in UC with squamous differentiation and small cell carcinoma of the bladder." (PMID 34851968, 2021).
solitary fibrous tumor (2 papers, 2014 to 2023). Solitary fibrous tumor (SFT) represents a diverse group of ubiquitous rare spindle cell neoplasms that may be benign or malignant and that most frequently arises from the pleura and peritoneum and rarely from other sites such as head and neck, liver and skeletal muscle. "Solitary fibrous tumors (SFTs) showed TERT promoter mutations in four cases (4/31; 13%), which were exclusively located at position C228T." (PMID 24726063, 2014).
spinal cord glioma (2 papers, 2020 to 2021). A neoplasm that arises from glial cells in the spinal cord. "The similar effect of TERT promoter mutation in spinal cord glioma was suggested in three cases." (PMID 32228694, 2020). "In the present study, we revealed that the rate of TERT promoter mutations was 22.4% (13/58); additionally, this mutation was found mainly in H3-wildtype tumors (9/13), and was associated with a poor prognosis for grade II/III spinal cord gliomas." (PMID 32228694, 2020).
T-cell acute lymphoblastic leukaemia (2 papers, 2015 to 2022). "The expression of CTC1, OBFC1, and TERT genes were found to be upregulated in both pediatric and adult B-cell ALL than in T-cell ALL cases but the difference was not statistically significant." (PMID 36233645, 2022).
thymic carcinoma (2 papers, 2023 to 2025). Thymic carcinoma (TC) is a type of thymic epithelial neoplasm characterized by a high malignant potential. "Interestingly, TERT promoter mutations were observed in a subset (22%) of intrathyroidal thymic carcinomas." (PMID 37249797, 2023). "Meanwhile, TERT promoter mutations have been identified in some ITTC cases but not in mediastinal thymic carcinomas, which may underlie their biological differences." (PMID 41476594, 2025).
thymic tumor (2 papers, 2020 to 2021). "Overall, TERT gene expression was low, with mean expression values less than one transcript per million (TPM) in every cancer type except thymic tumours." (PMID 33924498, 2021).
ulcerative colitis (2 papers, 2013 to 2023). An inflammatory bowel disease involving the mucosal surface of the large intestine and rectum. "Previous studies on precancerous lesions have identified telomere shortening in high-risk mucosa of ulcerative colitis and shown that telomere shortening and TERT expression in gastrointestinal metaplasia is associated with H. pylori infection." (PMID 36834592, 2023).
urothelial dysplasia (2 papers, 2020 to 2025). A morphologic finding indicating the presence of dysplastic changes in the transitional cell epithelium of the urinary tract. "We have reported that TERT C228T mutation was detected in 9% of normal bladder epithelium samples and in 27% of cases with urothelial dysplasia." (PMID 40995307, 2025). "Telomerase reverse transcriptase (TERT) C228T mutation was detected in normal urothelium and urothelial dysplasia of patients with nonmuscle invasive bladder cancer (NMIBC) and may thus be a novel and useful prognostic factor for risk stratification of NMIBC." (PMID 32533903, 2020).
acute coronary syndrome (1 paper, 2022). Signs and symptoms related to acute ischemia of the myocardium secondary to coronary artery disease. "These include the use of TERT-activating compounds in acute coronary syndrome, whether via canonical or non-canonical effects." (PMID 36552277, 2022).
acute monocytic leukemia (1 paper, 2023). Acute monoblastic leukemia (AML-M5), is one of the most common subtypes of acute myeloid leukemia (AML) that is either comprised of more than 80% of monoblasts (AML-M5a) or 30-80% monoblasts with (pro)monocytic differentiation (AML-M5b). "We expressed EGFP-GRAM-W in U2OS cells, macrophages differentiated from THP-1 cells (human monocytes derived from an acute monocytic leukemia patient), N/TERT cells (immortalized keratinocytes derived from fetal foreskin), HEK293T, and COS-7 cells." (PMID 37880244, 2023).
adenocarcinoma of the prostate (1 paper, 2012). "In addition, inhibition of progression of preneoplastic lesions (i.e., low and high-grade prostate intraepithelial neoplasms, PINs) to adenocarcinoma of the prostate by CDDO-Me in TRAMP mice was associated with significant decrease in TERT and its regulatory proteins in the prostate gland." (PMID 23519253, 2012).
adenoid cystic carcinoma (1 paper, 2023). A malignant tumor arising from the epithelial cells. "A mutation at the 146 nucleotide site (C250T) in the TERT promoter gene was detected by the Sanger sequencing method in an 82-year-old man with primary adenoid cystic carcinomas." (PMID 37383158, 2023). "Nonetheless, there are a few studies that report TERT promoter mutation in adenoid cystic carcinoma of the salivary gland, necessitating the need for further investigations." (PMID 37383158, 2023).